ACSL4 (acyl-CoA synthetase long chain family member 4)
Diseases named in the same sentence as ACSL4 in open-access papers (continued):
Sharing a sentence is not in itself a finding about the gene and the disease.
periodontitis (3 papers, 2023 to 2024). An acute or chronic inflammatory process that affects the tissues that surround and support the teeth. "The results showed reduced expression of GPX4 in both the gingiva and alveolar bone by immunofluorescence staining, consistent with a lower gingival Gpx4 level and higher Acsl4 and Ptgs2 levels by RT‒qPCR in the periodontitis group." (PMID 38670955, 2024). "The expression levels of ACSL4 and TfR1 were increased in the periodontitis group, and curcumin inhibited the expression of them." (PMID 37372983, 2023). "To further investigate the occurrence of ferroptosis in periodontitis, we tested the expression level of ferroptosis-markers such as ACSL4, SLC7A11, GPX4 and TfR1 in the gingival tissue." (PMID 37372983, 2023). "We found that the expression of ACSL4 and TfR1 was increased in ligature-induced periodontitis in mice, and curcumin significantly decreased the expression of ACSL4 and TfR1 in ligature-induced periodontal inflammation in mice." (PMID 37372983, 2023). "In ligature-induced periodontitis in mice, the expression level of ACSL4 and TfR1 were significantly increased, which would induce the initiation of ferroptosis, the while curcumin treatment can decrease the expression of those proteins." (PMID 37372983, 2023). "Moreover, ligature-induced periodontitis in mice treated with curcumin exhibited increased expression levels of SLC7A11 and GPX4 and decreased expression levels of ACSL4 and TfR1." (PMID 37372983, 2023).
renal carcinoma (3 papers, 2024 to 2025). A carcinoma arising from the epithelium of the renal parenchyma or the renal pelvis. "In future research, we will employ single-cell sequencing technology to analyze the differences in sensitivity to erastin/RSL3 among various renal cancer subpopulations characterized by differing ACSL4 expression levels." (PMID 41372608, 2025). "Knockdown of SPI1 induces ferroptosis in ccRCC may be caused by restoring the expression of ACSL4, a downstream target of SPI1 within renal cancer." (PMID 41372608, 2025). "In addition, we utilized clinical sample analysis to identify differential expression of SPI1 and ACSL4 in renal cancer, consistent with the TCGA database." (PMID 41372608, 2025). "The correlation between SPI1 and ACSL4 was studied in renal cancer cell lines and tissue samples." (PMID 41372608, 2025). "Additionally, we show that PRMT5 promotes the binding of ACSL4 to UBR5 via arginine 549 (R549) methylation, thereby inhibiting ferroptosis in renal cancer cells." (PMID 40756764, 2025). "Furthermore, we validated that knockdown of SPI1 combined with treatment erastin promotes renal cancer ferroptosis, elaborating on the mechanism that SPI1 interacts with EZH2 to mediate the transcriptional repression of ACSL4 targets by H3K27me3." (PMID 41372608, 2025).
renal failure (3 papers, 2023 to 2024). "Interestingly, increased ACSL4 expression in kidney bore a direct relationship with increasing plasma creatinine, suggesting that ferroptosis is the major cause of kidney failure in CP-AKI." (PMID 38097707, 2023).
rhabdomyolysis (3 papers, 2023 to 2025). Necrosis or disintegration of skeletal muscle often followed by myoglobinuria. "In HI studies, ACSL4 (a key ferroptosis enzyme) was identified as crucial in exertional heat stroke progression to rhabdomyolysis." (PMID 40920657, 2025). "Targeting ACSL4, either genetically or pharmacologically, significantly reduced muscle cell death and rhabdomyolysis biomarkers both in vitro and in vivo, suggesting ACSL4 inhibition is a promising therapeutic strategy to prevent EHS-induced rhabdomyolysis." (PMID 40703654, 2025).
steatosis (3 papers, 2017 to 2025). Increased lipid within the cytoplasm of cells. "Furthermore, liver-specific ACSL4 knockout improved steatosis and fibrosis in MCD diet-fed mice." (PMID 37569885, 2023).
subarachnoid hemorrhage (3 papers, 2021 to 2022). A serious neurological disorder characterized by intracranial hemorrhage into the subarachnoid space. "However, the function of ACSL4 in early brain injury (EBI) caused by subarachnoid hemorrhage (SAH) is unclear." (PMID 33314758, 2021). "Acsl4 (Ensmust00000112903) was found to be significantly increased in subarachnoid hemorrhage (SAH)." (PMID 35459923, 2022). "Qu et al41 found that ferroptosis was induced after subarachnoid hemorrhage by the elevated expression of Acyl‐CoA synthetase long‐chain family member 4 (ACSL4); inhibiting its expression or suppressing ferroptosis attenuated tissue damage and improved long‐term outcomes." (PMID 36184790, 2022).
acute liver failure (2 papers, 2020 to 2021). Rapid deterioration of liver function causing encephalopathy and coagulopathy. "Furthermore, APAP-induced acute liver failure is prevented by the pharmacological (i.e., Fer-1, DFO, and α-Toc) and genetic (i.e., ACSL4) inhibition of ferroptosis." (PMID 32094346, 2020).
asthma (2 papers, 2018 to 2024). "The level of ACSL4 was up-regulated in our Bet v 1-induced asthma mice model, which is consistent with other reports." (PMID 38395974, 2024). "It is an intriguing question for future research to investigate whether ACSL4-dictated ferroptosis in AT II cells is prevalent in asthma induced by different allergens." (PMID 38395974, 2024).
brain injuries (2 papers, 2022 to 2025). "Thus, ACSL4 may be a potential therapeutic target for ferroptosis inhibition in acute brain injuries." (PMID 35855863, 2022). "Likewise, traumatic brain injury-induced IL-23 upregulation enhanced neuronal ferroptosis through STAT3 activation, while IL-23 neutralization attenuated ferroptosis, restored GPX4 and ACSL4 expression, and normalized STAT3 overactivation." (PMID 41304754, 2025).
cardiac hypertrophy (2 papers, 2024). "We also identified ACSL4 as the major player upstream of ferroptosis, showing that it drives cardiac hypertrophy by activating the pyroptotic pathway." (PMID 39327446, 2024). "We found that neutralizing IL-1β in Acsl4 TG mice significantly reduced TAC-induced cardiac hypertrophy, improved cardiac systolic performance, prevented cardiomyocyte hypertrophy, and reduced all three markers of cardiac hypertrophy." (PMID 39327446, 2024). "Thus, both ferroptosis and lipid peroxidation appear to play an essential role in TAC-induced cardiac hypertrophy via ACSL4." (PMID 39327446, 2024). "Consistent with this notion, we also found that treating TAC-operated WT mice with PRGL493 and pioglitazone, two potent and selective inhibitors of Acsl4, partially protected against cardiac hypertrophy, reduced the expression of cardiac hypertrophy markers, and improved ventricular function." (PMID 39327446, 2024). "Notably, we also found that ALOX-mediated 12-HETE production plays a functional role in ACSL4-induced cardiac hypertrophy." (PMID 39327446, 2024). "Furthermore, we found that overexpressing Acsl4 selectively in cardiomyocytes promotes cardiac hypertrophy and the progression of HF by activating ferroptosis-induced pyroptotic signaling." (PMID 39327446, 2024). "We then asked whether overexpressing Acsl4 affected the progression of cardiac hypertrophy and altered cardiac function after pressure overload (i.e., TAC) by examining control and Acsl4 TG mice 3 weeks after sham or TAC surgery." (PMID 39327446, 2024). "In addition, TAC increased the levels of all three markers of cardiac hypertrophy (namely, β-MHC, RCAN1.4, and ANF) in the Acsl4 F/F mice, and this increase was virtually eliminated in TAC-operated Acsl4 KO mice." (PMID 39327446, 2024). "Moreover, we found that the expression of Il1b and Nlrp3 (which encode the cytokine IL-1β and the pyrin-like protein NLR family pyrin domain containing 3, respectively) were significantly upregulated in TAC-induced cardiac hypertrophy in Acsl4 F/F mice, but not in Acsl4 KO mice." (PMID 39327446, 2024). "Given our finding that cardiomyocytes lacking Acsl4 have reduced TAC-induced lipid peroxidation, we next asked whether inhibiting lipid peroxidation affects the progression of cardiac hypertrophy in Acsl4 TG mice." (PMID 39327446, 2024).
cardiomyopathy (2 papers, 2021 to 2023). A disease of the heart muscle or myocardium proper. "Thus, miR-130b-3p may ameliorate LPS-induced cardiomyopathy by regulating the ACSL4 and AMPK signaling pathways." (PMID 37705752, 2023).
chronic prostatitis (2 papers, 2022 to 2023). An infectious or non-infectious chronic inflammatory process that affects the prostate gland. "In this study, the inactivation of the system Xc−/GPX4 axis, accumulation of iron, and activation of ACSL4/LPCAT3 axis strongly highlighted the important role of ferroptosis on prostatitis development." (PMID 35755168, 2022). "Moreover, elevated iron concentration and differential expression of ferroptosis indicators, including GPX4, SLC7A11/Xc−, ACSL4, LPCAT3, and PTGS2, implied that ferroptosis engaged in the development of prostatitis in the context of iron overload and oxidative damage." (PMID 35755168, 2022).
cutaneous melanoma (2 papers, 2022 to 2026). A primary melanoma arising from atypical melanocytes in the skin. "Higher ACSL4 expression was consistently associated with improved OS, MFS, and DFS in cutaneous melanoma." (PMID 41918944, 2026).
Depression (2 papers, 2025). "The inhibition of ACSL4 by rosiglitazone could significantly attenuate impulsive and depression-like behaviors in MRL/lpr mice, with increased expression of GPX4 and decreased lipid peroxidation indicators in the brain parenchyma." (PMID 40332005, 2025).
endometriosis (2 papers, 2024 to 2025). The growth of functional endometrial tissue in anatomic sites outside the uterine body. "Fatty acid synthase 4 (ACSL4) plays a crucial role in fatty acid metabolism and is closely linked to immune cell infiltration in endometriosis, mainly because ACSL4 plays a key role in fatty acid metabolism." (PMID 40313549, 2025). "Follow-up studies can further explore the improvement of clinical symptoms in patients with endometriosis by regulating ACSL4 expression activities, which will be a potential therapeutic development direction." (PMID 40313549, 2025). "This retrospective case–control study provides a comprehensive immunohistochemical assessment of the expression and tissue distribution of established ferroptosis markers: GPX4, ACSL4, and TfR1 in endometriosis patients." (PMID 39062590, 2024). "This suggests that ACSL4 is not only involved in regulating fatty acid metabolism but also directly affects the function and infiltration patterns of immune cells, making them play a more effective role in the microenvironment of endometriosis." (PMID 40313549, 2025). "Therefore, understanding the specific mechanisms of ACSL4 in immune cell infiltration will help uncover the pathological mechanisms of endometriosis and provide new targets for future therapeutic strategies." (PMID 40313549, 2025). "In endometriosis, the expression of ACSL4 may be closely related to the synthesis of pro-inflammatory cytokines, which will lead to increased infiltration of immune cells in ectopic tissues, aggravating local inflammatory responses and corresponding symptoms." (PMID 40313549, 2025). "Statistically significant differences were observed in the expression levels of six hub genes (ACSL4, CYP2C18, CYP2C9, HSD17B3, HSDL2, and PTGS2) between the Endometriosis and Control groups of the combined GEO datasets (p < 0.001)." (PMID 40313549, 2025).
erectile dysfunction (2 papers, 2023 to 2026). Persistent or recurrent inability to achieve or to maintain an erection during sexual activity. "In conclusion, overexpression of PRDX2 in ADSCs enhanced the therapeutic effect in a rat model of neurogenic erectile dysfunction by inhibiting ferroptosis via regulation of the GPX4/ACSL4 axis." (PMID 36819780, 2023). "Our results further demonstrated changes in the expression of key proteins (GPX4 and ACSL4) in the ferroptosis pathway, whereas PRDX2-ADSCs ameliorated BCNI-induced erectile dysfunction and ferroptosis of the corpus cavernosum in NED rats." (PMID 36819780, 2023).
fibrosarcoma (2 papers, 2018 to 2025). A malignant mesenchymal fibroblastic neoplasm affecting the soft tissue and bone. "In this study, immunohistochemical screening of multiple soft tissue tumour arrays revealed that ACSL3 and ACSL4 were highly, but differentially, expressed in a subset of leiomyosarcomas, fibrosarcomas and rhabdomyosarcomas, with consistent cytoplasmic and granular stainings of tumour cells." (PMID 29450800, 2018).
gastric adenocarcinoma (2 papers, 2024 to 2026). "Through the GEPIA database we determined the co-expression of ACSL4 and A20 in gastric adenocarcinoma." (PMID 38370339, 2024).
hepatic (2 papers, 2024). "This study highlighted the vital function of ACSL4 in the occurrence and progression of hepatitis HBV‐HCC." (PMID 39268355, 2024).
infertile (2 papers, 2024). "Because of the prominent expression of ACSL4 in uterine epithelium, we speculated that inactivation of Acsl4 may rescue infertility caused by Gpx4 depletion in the uterine epithelium." (PMID 38044324, 2024). "Comparing the variables in the three examined groups, elevated levels of ACSL4 were observed in infertile patients with urogenital infections and varicocele; GPX4 levels were similar in the three groups." (PMID 39273059, 2024).
intervertebral disc degeneration (2 papers, 2025). "Glycolysis‐derived lactate activates nucleus pulposus cell ferroptosis via Histon H3K18la‐mediated ACSL4 transcription and ACSL4 lactylation and aggravate intervertebral disc degeneration." (PMID 40171826, 2025). "Another study reported that lactate enhances H3K18la expression, thereby promoting ACSL4 upregulation and activating ACSL4-mediated ferroptosis during intervertebral disc degeneration." (PMID 41461917, 2025).
kidney injury (2 papers, 2023 to 2024). Trauma to the kidney. "In this study, we show that ACSL4 is overexpressed by tubular epithelium in a model of ER-stress-induced kidney injury and is upregulated in response to STAT3 signaling in a cell extrinsic manner." (PMID 38799564, 2024).
kidney stone (2 papers, 2023 to 2025). "The knockdown of CHAC1 significantly reversed the GPX4 and XCT protein deficiency in the mouse kidney stone model, and the upregulation of ACSL4 and CD71 protein was also mildly regained." (PMID 39836526, 2025). "Furthermore, qPCR and fluorescence immunohistochemistry results demonstrated increased ACSL4 expression in the kidney tissues derived from patients with kidney stones than in normal kidney tissue." (PMID 37893066, 2023).
lupus (2 papers, 2023 to 2025). "Notably, our findings demonstrated that the use of rosiglitazone by suppressing ACSL4 dramatically ameliorated the brain damage in lupus mice compared to control mice." (PMID 40332005, 2025). "We also observed a significant negative correlation between ACSL4 expression in the lupus tubulointerstitium tissue and glomerular filtration rate (GFR) in patients (R2 = 0.5610, p < 0.0001)." (PMID 37153759, 2023).
nasopharyngeal carcinoma (2 papers, 2025). A carcinoma arising from the nasopharyngeal epithelium. "In present study, we found that the acetylation of acyl-CoA synthase long-chain family member 4 (ACSL4) enhances its protein stability and a double-edged sword regulation in nasopharyngeal carcinoma (NPC)." (PMID 40050614, 2025). "In nasopharyngeal carcinoma, HDAC2 was shown to enhance ACSL4 acetylation, thereby promoting ferroptosis and radiosensitivity." (PMID 40947430, 2025).
pancreatitis (2 papers, 2024 to 2025). Inflammation of the pancreas. "Recent studies have highlighted the suppression of ferroptosis as a potential therapeutic strategy for pancreatitis, possibly through enhancing antioxidant enzymes such as GPX4, promoting iron efflux or sequestration, and reducing pro-ferroptotic proteins like ACSL4." (PMID 41470786, 2025).
pulmonary fibrosis (2 papers, 2024 to 2025). Chronic progressive interstitial lung disorder characterized by the replacement of the lung tissue by connective tissue, leading to progressive dyspnea, respiratory failure, or right heart failure. "Our findings revealed that the expression of ACSL4 was elevated in both the 7-day and 21-day models compared to the control groups, suggesting a role for ACSL4 in the initiation and progression of pulmonary fibrosis." (PMID 40867551, 2025). "We selected two time points to observe, day 7 and day 21, to assess the role of ACSL4 in different stages of pulmonary fibrosis." (PMID 40867551, 2025). "To explore the involvement of ACSL4 in pulmonary fibrosis, we assessed its expression at this stage." (PMID 40867551, 2025). "Taken together, our findings not only confirm a role for ACSL4 in pulmonary fibrosis but also uncover a previously unrecognized upstream pathway—C5a/C5aR1–calcium signaling—that regulates its expression in fibroblasts." (PMID 40867551, 2025). "Pharmacological inhibition of ACSL4 attenuated the differentiation of myofibroblasts and alleviated pulmonary fibrosis." (PMID 40867551, 2025). "To further explore the function of ACSL4 in the early stage of pulmonary fibrosis, we utilized PRGL493, a potent and selective ACSL4 inhibitor." (PMID 40867551, 2025). "The potential role of ACSL4 in pulmonary fibrosis, particularly in regulating fibroblast activation and FMT, remains largely unexplored." (PMID 40867551, 2025). "Activation of this signaling contributes to the pathogenesis of pulmonary fibrosis by upregulating ACSL4 expression and promoting FMT." (PMID 40867551, 2025). "In bleomycin (BLM)-induced pulmonary fibrosis of C57BL/6JGpt mice, and in C5a-stimulated primary lung fibroblasts, the expression of ACSL4 was markedly upregulated." (PMID 40867551, 2025). "Therefore, targeting the C5a/C5aR1–calcium–ACSL4 axis could effectively ameliorate fibrotic progression by reducing fibroblast activation and migration, potentially offering a novel therapeutic strategy for pulmonary fibrosis treatment." (PMID 40867551, 2025). "Interestingly, APD downregulates ACSL4, PTGS2, and ROS while upregulating GPX4 and SLC7A11, indicating its role in inhibiting ferroptosis in pulmonary fibrosis." (PMID 38584671, 2024). "However, the relationship between C5a/C5aR1 signaling and ACSL4 in pulmonary fibrosis has not been elucidated." (PMID 40867551, 2025).
sarcoma (2 papers, 2018 to 2022). A usually aggressive malignant neoplasm of the soft tissue or bone. "ACSL4 mutation caused significant changes of immune infiltration in UCEC (Uterine Corpus Endometrial Carcinoma) and SARC (Sarcoma)." (PMID 35126480, 2022).
Sjögren’s syndrome (2 papers, 2024 to 2025). "Genistein exerts protective and anti-inflammatory effects on salivary glands in Sjögren’s syndrome by inhibiting Xist/ACSL4-mediated ferroptosis following binding to estrogen receptor-α." (PMID 40934008, 2025).
transient cerebral ischemia (2 papers, 2021 to 2022). "A transient cerebral ischemia model was established for mice by middle cerebral artery occlusion (MCAO); glutathione peroxidase 4 (GPx4), ACSL4 and cyclooxygenase 2 (COX2) were detected by Western blot, and changes to mitochondria were observed by a transmission electron microscope." (PMID 33889074, 2021).
abortion (1 paper, 2021). the ending of pregnancy by removing a fetus or embryo before it can survive outside the uterus. "By investigating rat abortion model, the results showed NLRP1 and NLRP3 expression in abortion rat uterus increased (∗P < 0.05, ∗∗P < 0.01), TFR1 and ACSL4 expression increased and GPX4 expression was decreased (∗P < 0.05, ∗∗P < 0.01), that compared with the control group." (PMID 34490257, 2021).